RAP2B (RAP2B, member of RAS oncogene family)
Diseases named in the same sentence as RAP2B in open-access papers (continued):
Sharing a sentence is not in itself a finding about the gene and the disease.
tumor (19 papers, 2010 to 2025). "Our findings suggest that Rap2B inhibits the polymerization of F-actin, thereby affecting intestinal barrier integrity and tumor cell migration, ultimately promoting the development and progression of CRC." (PMID 40223002, 2025). "Previous studies, including our own, have shown that Rap2B is highly expressed in various human cancers and acts as an oncogene in multiple tumor types in vitro." (PMID 40223002, 2025). "Our analysis revealed a positive correlation between high Rap2B levels and prognostic factors such as histological grade, tumor stage, lymph node (LN) metastasis, and depth of invasion." (PMID 40223002, 2025). "Our experiments indeed demonstrated that Rap2b expression is significantly higher in migrating cells compared to cells originating from the primary tumor." (PMID 39277583, 2024). "The Wilcoxon rank-sum test was used to evaluate expression levels, and we found that MIDN, COMTD1, and RAP2B were highly expressed in tumor tissues and lowly expressed in normal tissues." (PMID 37405477, 2023). "Previous studies have shown that RAP2B plays a vital role in signal transduction, cell adhesion, proliferation, and metastasis in human tumor cells." (PMID 35260078, 2022). "miR-22-3p’s downstream target gene is RAP2B, located on 3q25.2, an oncogene that is highly expressed in a variety of tumours and plays an important role in promoting tumour cell proliferation and metastasis." (PMID 36338118, 2022). "miR-194/192 targets genes are responsible for glucose metabolism (Gyg1), EMT (Msn), tumor growth (Rap2b and Ereg), as well as cell adhesion (Alcam)." (PMID 34771521, 2021). "Rap2B highly expressed in various human tumors, participating tumor cell proliferation, migration and invasion regulation." (PMID 32596241, 2020). "Except for RAP2B all genes upregulated in zebrafish were also upregulated in at least one tumor type in medaka." (PMID 22693581, 2012). "In addition, as shown by immunohistochemistry of CSCC FFPE preparations, RAP2B is expressed only in the basal epidermal layer of healthy skin but in almost all cells of the tumor." (PMID 36499729, 2022). "Moreover, tumor xenografts were also performed to confirm the functions of PRPF3 and RAP2B in vivo, and the results showed that the downregulation of TMEM43, PRPF3, and RAP2B obviously reduced tumor growth in MIAPaCa-2 cells." (PMID 35260078, 2022). "Most studies about RAP2A and RAP2B focus on their functions in tumor." (PMID 34733151, 2021). "RAP2B located on 3q25.2 is an oncogene that is highly expressed in a variety of tumors and plays an important role in promoting biological processes (such as tumor cell proliferation, metastasis, etc.)." (PMID 34239562, 2021). "Results showed that the expression of Rap2B is higher in tumor cells than in normal cells." (PMID 26201295, 2015). "Moreover, considering that metastasis is a multi-step process starting with the release of invasive cells from the primary tumor, we investigated whether migrating cells express more Rap2b than cells from the primary tumor itself." (PMID 39277583, 2024). "We first assessed Rap2B expression in 286 CRC samples and 41 non-tumor samples from The Cancer Genome Atlas (TCGA)." (PMID 40223002, 2025). "The results showed that Rap2B was significantly upregulated in CRC tissues compared to non-tumor tissues." (PMID 40223002, 2025).
tumor (continued). "In addition, hBM-MSC-Exo and hUC-MSC-Exo containing tumor-suppressive miRs (miR-3940-5p/miR-22-3p/miR‐16‐5p) have been shown to suppress proliferation, migration, and invasion of CRC cells via regulation of RAP2B/PI3K/AKT signaling pathway and ITGA2/ITGA6." (PMID 35365226, 2022). "Previous publications have revealed that RAP2B might be related to an advanced tumor stage and grade in ESCC, while no study has been conducted to demonstrate the expression and function of other CFRGs in ESCC." (PMID 37405477, 2023).
cancer (18 papers, 2014 to 2025). A tumor composed of atypical neoplastic, often pleomorphic cells that invade other tissues. "Rap2b belongs to the Ras superfamily, which is closely associated with tumorigenesis and cancer progression in humans." (PMID 39277583, 2024). "In contrast, CDKN1A has positive co-dependency with PHLDA3, another factor involved in the intrinsic apoptotic pathway and RAP2B, which is implicated in proliferation and migration of cancer cells." (PMID 36681780, 2023). "While Rap2B, a member of the Ras superfamily, has been linked to cancer malignancy in vitro, its exact role in tumorigenesis remains unclear." (PMID 40223002, 2025). "The isoform Rap2B was initially cloned from a platelet cDNA library, and is located at 3q25.2 on the human chromosome, a known hotspot in cancer research." (PMID 40223002, 2025). "Data demonstrated that the co-delivery of both Adr and siRap2b with GN particles into cancer cells decreased Rap2b expression by siRap2b, boosting the anticancer therapeutic efficiency of Adr." (PMID 38951806, 2024). "designed a (gene/ drug) nano-carrier for Rap2b siRNA delivery to evaluate its therapeutic potential against human cancers." (PMID 38951806, 2024). "RAP2B is a protein-encoding gene in the RAS oncogene family and is involved with the proliferation and migration of various cancer types." (PMID 37854252, 2023). "knockdown of Rap2B inhibits the growth, migration and invasion of cancer cells through ERK1/2 signaling pathway." (PMID 30064475, 2018). "In the present study, we designed a nanostructure-based drug/gene delivery system to evaluate the potential of Rap2b siRNA as a therapeutic agent against human cancers." (PMID 28423503, 2017). "Knockdown of Rap2b sensitizes HCT116 cells to adriamycin-induced apoptosis, indicating that Rap2b promotes adriamycin resistance in cancer cells." (PMID 28423503, 2017). "As expected, regardless of conjugation to GNs, siRap2b significantly down-regulated the expression of Rap2b in cancer cells." (PMID 28423503, 2017). "Notably, previous studies in diverse cancer models have identified Rap2B as a multifunctional GTPase that directly drives tumorigenic processes, such as enhancing proliferation via activation of the ERK/MAPK and PI3K/Akt signaling pathways." (PMID 40223002, 2025). "Our findings have uncovered a previously unknown pathological mechanism in which Rap2b palmitoylation promotes cancer progression." (PMID 39277583, 2024). "Interestingly, regarding the impact of Rap2b levels on patient survival, the analysis indicated that a high level of Rap2b is negatively correlated with the survival of cancer patients in the CMS1–3 categories (p = 0.02 in CMS1), but not in CMS4." (PMID 39277583, 2024). "RAP2B has been reported to be an oncogene that may be correlated with cancer progression by regulating ERK phosphorylation levels." (PMID 35260078, 2022). "As forementioned, Rap-2b is classified as an oncogene and it is over-expressed in cancers." (PMID 31817608, 2019). "Rap2B is a Ras family protein and is upregulated in many tumors, which could be a new therapeutic target for cancer." (PMID 29029384, 2017). "We found that Rap2B was highly expressed in multiple human cancers." (PMID 29029384, 2017).
cancer (continued). "Our RNAseq data also indicated that Rap2B was mainly involved in the regulation of focal adhesion, actin cytoskeleton regulation and cancer pathways, suggesting that Rap2B may play a pivotal role in mechanical signal transduction, particularly in cytoskeletal remodeling and cell adhesion." (PMID 40223002, 2025). "Collectively, these findings elucidate a novel Rap2B-plectin-F-actin axis driving CRC tumorigenesis and progression, refining mechanistic insights into Ras-family-mediated cytoskeletal remodeling in cancer pathogenesis." (PMID 40223002, 2025). "RAP2B is a RAS oncogene family member gene, reported to up regulate in various human cancers and involves in the progression of cancer." (PMID 30212456, 2018). "Recently, we have reported that Rap2b possesses a pro-survival function in cancer cells, indicating that Rap2b is a nonpump resistance gene and a promising anticancer target." (PMID 28423503, 2017). "One such candidate gene was Rap2B, a member of the Ras family; moreover, we found that most carcinoma cells expressed higher levels of Rap2B than in the non-cancerous immortalized BJ or WI-38 cell lines." (PMID 29029384, 2017).
infection (2 papers, 2012 to 2019). The state of being infected such as from the introduction of a foreign agent such as serum, vaccine, antigenic substance or organism. "Taking into account that overexpression of Rap2b wt alters both, heterotypic and homotypic fusions with the C. burnetii vacuoles, at later times of infection, we were interested in assessing the possible mechanism involved at the molecular level." (PMID 30763357, 2019). "Hence, the over-expression of this protein would decrease the heterotypic fusion capacity between vesicles or lysosomes containing dextran, which is indicative that heterotypic fusion is affected by overexpression of Rap2b wt at later times of infection." (PMID 30763357, 2019). "In cells overexpressing wt EGFP-Rap2b a decrease was observed in both homotypic and heterotypic fusion events of the CRV at later times of infection (i.e. 48 h), suggesting that Rap2b wt acts mainly at later times during the infection." (PMID 30763357, 2019).
bacterial infection (1 paper, 2012). "To confirm the participation of this cAMP/EPAC/Rap2b pathway in the bacterial infection process, we used different S. aureus Hla positive and null strains." (PMID 22654658, 2012).
RAP2B also shares sentences with these, for which no sentence is quoted: acute myeloid leukemia (1 paper); cervical cancer (1); Esophageal Neoplasms (1); glioblastoma (1); helminth infections (1); Hyperkeratosis (1).